TET2 (tet methylcytosine dioxygenase 2)
Diseases named in the same sentence as TET2 in open-access papers (continued):
Sharing a sentence is not in itself a finding about the gene and the disease.
tumor (continued). "TET2 and DNMT3A mutations can occur in hematopoietic progenitor cells, driving clonal hematopoiesis and tumor transformation." (PMID 40394210, 2025). "In TCGA database, tumor TET2, STAT5A, and cGAS expressions positively correlated with vascular normalization-associated genes including vascular stabilization, endothelial-lymphocyte interaction, pericytes and T cell chemotaxis." (PMID 38177099, 2024). "Collectively, these findings imply that pharmacological VC not only activates tumor cGAS through cytoplasmic dsDNA leakage, but also increases tumor cGAS expression via epigenetic modifications by Tet2-dependent DNA demethylation." (PMID 38177099, 2024). "Consistently, presentation of the OVA tumor antigen was enhanced by TET2 following IFN-γ stimulation, which was further stimulated by VC treatment, and effective in vitro cytotoxic activity of T cells requires TET2 tumor expression." (PMID 39388288, 2024). "TET2, ten-eleven translocation 2, acts as a tumor-suppressor in many types of cancer via its enzymatic DNA demethylation activity." (PMID 38499482, 2024). "In contrast, DNMT3a-TET2 crosstalk silences tumor suppressors (i.e., P15, SOCS2) through a corepressor complex with HDAC2 along with increased promoter DNA methylation." (PMID 38528605, 2024). "Mechanistically, TET2 mediated IL-2/STAT5A signaling epigenetically upregulates tumor cGAS expression and produces cGAMP." (PMID 38177099, 2024). "Using intercellular communication analysis from the scRNA-seq data, we show that loss of TET2 expression in the B16 tumors leads to loss of IFN-γ expression in T cells, which then reduces IFN-γ–induced responses in the tumor and tumor microenvironment." (PMID 39388288, 2024). "We revealed the relationship between TET2 upregulation, demethylation and tumor suppressor re-expression, and concomitant resistance to DNMTi in the absence of the DNMT1 gene." (PMID 39057134, 2024). "In vivo studies in male mice also reveal that administration of vitamin C, a promising anti-cancer agent, stimulates TET2 activity, induces tumor vascular normalization and enhances the efficacy of anti-PD-L1 therapy alone or in combination with IL-2." (PMID 38177099, 2024). "High Tet Methylcytosine Dioxygenase 2 (TET2) expression was observed in multiple slow cycling dormant-like tumor subsets." (PMID 38426087, 2024). "AMPK also directly phosphorylates TET2, enhancing its tumor-suppressive activity and modulating tumor suppression." (PMID 39062614, 2024). "This makes lenvatinib particularly beneficial for patients with low NAD+ levels or high TET2 expression, as it modulates both tumor metabolism and immune responses to inhibit tumor progression." (PMID 39461979, 2024). "In primary tumor cells, IL-6 expression is increased by DNA demethylation of its promoter via ten-eleven translocation 2 (Tet2)." (PMID 39199304, 2024). "Consistent with the tumor growth data, VC combined with anti–PD-L1 yielded optimal survival only in the TET2-WT tumors." (PMID 39388288, 2024). "OVA antigen presentation was increased by more than 3-fold in the WT tumor cells after VC treatment, while remaining largely unchanged in the TET2-KO tumor cells." (PMID 39388288, 2024). "TET2 expression in the tumor cells is essential for activation of tumor-infiltrated T cells and establishing IFN-γ–regulated tumor communication." (PMID 39388288, 2024). "Methylation β values of DNMT3A and TET2 were significantly correlated with gender, tumor size, extent of invasion, and clinical stage (P < 0.05)." (PMID 38246976, 2024). "In DNMT1–/– cells, decitabine robustly upregulates TET2, with re-expression of tumor suppressors at 0.5 μM and 5 μM doses and aza-T-dCyd at a 0.5 μM dose only upregulates TET2 and induces p16ink4A re-expression." (PMID 39057134, 2024).
tumor (continued). "The present study shows that TET2 upregulates tumor cGAS expression to produce cGAMP, which further activates STING pathway in endothelial cells, leading to tumor vascular normalization and enhanced intratumoral CD8+ T cell infiltration." (PMID 38177099, 2024). "On the other hand, TET2 inactivation in tumor infiltrating lymphocytes and myeloid cells has also been shown to inhibit tumor growth, indicating a dependence on other factors." (PMID 39172974, 2024). "Consistently, VC promoted antigen presentation in cell-based and tumor assays in a TET2-dependent manner." (PMID 39388288, 2024). "Tumor NGS results were still pending, and his liquid biopsy (FoundationOne® Liquid CDx; Foundation Medicine, Inc., Cambridge, MA, USA) showed a low ctDNA tumor fraction (<1%) and detectable mutations in DNMT3A and TET2 suspicious for clonal hematopoiesis." (PMID 39449891, 2024). "Compared with PBS control, VC treatment increased the expression of TAP1 in the tumor clusters, but remained largely unchanged between WT and TET2-KO tumors." (PMID 39388288, 2024). "The analysis of differential methylation sites between tumor and normal samples revealed that cg01210909, cg09666717, and cg12306086 exhibited hypermethylation in TET2." (PMID 38356721, 2024). "In this work, we provide evidence that stimulating TET2 activity by VC combined with VC-induced dsDNA leakage activate tumor cGAS-cGAMP-endothelial STING pathway and promote lymphocyte trafficking." (PMID 38177099, 2024). "To analyze the effects of VC and TET2 on the tumor microenvironment and on gene expression responses in tumor cells, we performed scRNA-seq analysis." (PMID 39388288, 2024). "Overall, augmentation of TET2 and activation of tumor suppressors had minimal effects on altering the resistance to DNMTi conferred by DNMT1 gene deletion." (PMID 39057134, 2024). "The expression of TET2, in tumor samples such as BRCA, COAD, HNSC, KIRP, READ, and THCA, was lower, while in CHOL, GBM, KIRC, and UCEC tumors, it was significantly higher than that in corresponding normal control tissues." (PMID 39104395, 2024). "VC treatment enhanced IFN-γ expression in T cells and IFNGR1 in tumor cells, which was dependent on the expression of TET2 in tumors." (PMID 39388288, 2024). "The methylation degrees of DNMT3A and TET2 were statistically analyzed in correlation with clinical and pathological features (gender, age, lesion site, tumor size, clinical stage, pathological stage, and lymphatic metastasis)." (PMID 38246976, 2024). "Intercellular communication analysis of the scRNA-seq data showed that TET2 tumor expression was required for T cell activation and subsequent IFN-γ–controlled signaling events, which were strongly enhanced by VC treatment." (PMID 39388288, 2024). "We observed increased expression of B2M in the WT tumor cells treated with VC, which was reduced in the TET2-KO cells." (PMID 39388288, 2024). "Together, these data suggest that the ability of VC to enhance T cell responses is partly dependent on TET2-mediated upregulation of antigen presentation genes and machinery in tumor cells." (PMID 39388288, 2024). "We revealed the relationship between TET2 upregulation, demethylation, and tumor suppressor re-expression, and concomitant resistance to DNMTi in the absence of DNMT1." (PMID 39057134, 2024). "Subcutaneous injection of Huh 7-MDR-TET2, Huh 7-MDR-Mock, Huh 7-shTET2, and Huh 7-shNC in mice revealed that when treated with chemotherapy agents, tumor growth of HCC cells with high expression of TET2 was significantly inhibited." (PMID 36732324, 2023). "TET2 is known to have pleiotropic functions in different immune cells known to play a role in tumor immunity, including macrophages/monocytes, CD4+ helper T cells, T regulatory cells, CD8+ T cells and B cells." (PMID 37841428, 2023). "We found TET2 KO promotes ammonia consumption in tumor cells, and the growth-inhibiting effect on tumor cells by exogenous ammonia can be relieved by knockout of TET2." (PMID 37550284, 2023).
tumor (continued). "In CD8+ T cells, TET2 represses memory differentiation following infection, though less is known about the role of TET2 deficiency in CD8+ T cell anti-tumor immunity and T cell exhaustion." (PMID 37841428, 2023). "TET2-knockout mice have increased IL-6 levels in the seeded tumor tissue, which in turn stimulates the recruitment of immunosuppressive granulocyte myeloid-derived suppressor cells (G-MDSCs) and reduces the number of CD8 T cells during antitumor therapy." (PMID 37488178, 2023). "In summary, this study establishes a functional link between TET2 and mTORC1, two major regulators of tumor growth, and provides a molecular mechanism through which TET2 suppresses mTORC1 signaling." (PMID 37550284, 2023). "The TET2-mediated anti-tumor effects of AICAR on CRC in vivo and the clinical significance of the results of this study require further evaluation." (PMID 36806702, 2023). "All of these results demonstrate that TET2, especially its localization and activity, is a new therapeutic intervention target for life-threatening late-stage tumours." (PMID 37620362, 2023). "Mutations in MLL2 (KMT2D) and TET2 were associated with inferior prognosis in ENKTL, and overexpression of EZH2 was associated with higher tumor cell proliferation, advanced stage, and inferior survival." (PMID 36900160, 2023). "In our study, we found that elevated β-catenin translocates TET2 from the cytosol to the nucleus and suppresses tumour growth." (PMID 37620362, 2023). "Taken together, these findings indicate that TET2 inhibits tumour cell growth and metastasis by activating demethylation activity via regulation of RORA-SPARC expression." (PMID 37620362, 2023). "As an epigenetic modifier, TET2 has fundamental roles in cell fate determination, cell differentiation and tumor development." (PMID 37550284, 2023). "Whole-exome sequencing revealed 99 somatic mutations including SMARCA4, ARID2, TET2, CDKN2A, WNT7A, NOTCH3 and STAG2, all present both in the primary tumor and in the cell line." (PMID 38201285, 2023). "Blocking the PCIF1-CTBP2 complex impaired the tumorigenic abilities of tumor cells partially as a result of activated translation of TET2 tumor suppressor." (PMID 37643007, 2023). "Here, we reported that TET2 modulates cellular arginine concentration through urea cycle by mRNA oxidation and suppresses mTORC1 signaling, thus inhibiting tumor cell growth." (PMID 37550284, 2023). "In HNSCC tumor tissues, increased CpG73 methylation levels were in correlation with decreased mRNA expression of TET2 (p < 0.05) and TDG (p < 0.01)." (PMID 37367043, 2023). "AMPK activator metformin activated AMPK and thus elevated the total TET2 levels in hyperglycemic mice, significantly reducing tumor growth in vitro and in vivo." (PMID 36979633, 2023). "Fortunately, TET2 KO significantly sensitizes a variety of tumor cells to mTORC1 inhibition by rapamycin, temsirolimus or everolimus, which is recaptured in mouse model." (PMID 37550284, 2023). "IM12 and Vc promoted the nuclear localization and catalytic activity of TET2 and synergistically suppressed tumour cell growth in vivo and in vitro." (PMID 37620362, 2023). "In summary, RORA and SPARC are crucial downstream targets of TET2 that connect TET2 and its tumour suppression effects." (PMID 37620362, 2023). "In this study, U2AF1, DNMT3A, SF3B1, and EZH2 in the secondary tumor group was higher than that in the tumor‐free group, while the mutation rate of ASXL1, TET2, and KMT2D was higher in the tumor‐free group." (PMID 36727544, 2023). "Clearly, the tumours derived from TET2-overexpressing A549 cells were smaller than those derived from the vector control A549 cells." (PMID 37667220, 2023). "In erasers, TET1 and TET3 were highly expressed in tumor tissues, while TET2 was down-regulated in tumor tissues." (PMID 37907576, 2023).
tumor (continued). "Here we report a case of BPDCN with a novel AFF4::IRF1 fusion predicted to lead to a loss-of-function of the IRF1 tumor suppressor, somatic mutations of ASXL1, TET2, and MYD88, as well as multiple intrachromosomal deletions." (PMID 38203475, 2023). "TET2 is well recognized as a transcriptional regulatory factor and tumor suppressor in numerous tumors." (PMID 37643007, 2023). "Further studies indicate that miR-22-3p directly targets TET2, and chronic alcohol intake instigates HCC tumor formation via the β-catenin/miR-22-3p/TET2 axis." (PMID 38111040, 2023). "Further examination with immunoprecipitation–mass spectrometry illustrated that β-catenin activation was indispensable for the nuclear localization and tumour suppression effects of TET2." (PMID 37620362, 2023). "Among the differentially expressed genes present, DNMT1, NSUN2, NSUN4, and TET2 were highly expressed in LNM + tumor tissues while NSUN5 and NSUN7 expression was reduced." (PMID 37907576, 2023). "In each patient, and in agreement with the original report, we discovered a cluster(s) corresponding to the neoplasm along with the corresponding driving mutations in JAK2, DNMT3A and TET2 genes." (PMID 37026484, 2023). "We then used the m6Am-Seq method to profile the mRNA m6Am site at single-base resolution and found that mRNA of TET2, a well-known tumor suppressor, was a major target substrate of the PCIF1-CTBP2 complex." (PMID 37643007, 2023). "Rapamycin treatment dramatically diminishes the TET2 KO tumor growth, while only has moderate efficacy to WT tumors." (PMID 37550284, 2023). "These genes display great potential as a novel therapeutic target and hence it will be of importance to delineate the extent to which they are correlated with cell survival in TET2 tumour models." (PMID 36989121, 2023). "Although mutations of TET1 or TET3 are rarely detected in hematopoietic malignancies, in most TET2MT malignancies, TET1 and TET3 function as tumor repressors by compensating for TET2 activity." (PMID 36203205, 2022). "Phosphorylation of TET2 at Ser99 by AMP-activated kinase (AMPK) enhances its tumor suppression by stabilizing TET2." (PMID 35659740, 2022). "In vivo delivery of a miR-10b-5p inhibitor that normalizes TET2 expression and 5hmC levels inhibits tumor growth and prolongs survival of animals bearing pre-established orthotopic GBM xenografts." (PMID 35136034, 2022). "We also show that TET2 knockdown using two independent shRNA hairpins efficiently decreases 5hmc levels and significantly enhances self-renewal and tumor growth capacity of GSC isolates." (PMID 35136034, 2022). "In contrast, in lung cancer the TET2 knockout in myeloid cells promoted angiogenesis and tumor progression via a S100A8/A9 - VEGFα loop." (PMID 35663987, 2022). "The mutational landscape of AITL/TCL‐TFH has been well characterized, with frequent early occurrence of TET2 and DNMT3A mutations in haematopoietic stem cells, and RHOA‐G17 and IDH2‐R172 mutations as later pathogenic events in tumour cells only." (PMID 35064935, 2022). "TET2 mutations represent early genetic lesions that occur in upstream hematopoietic stem/progenitor cells (HSC/HPC) and have been detected in both tumor tissue and normal blood cells of patients with AITL." (PMID 36428791, 2022). "While both TET2 and DNMT3A were tumor suppressive in MDS, this study showed that DNMT3A loss is the primary or causative genomic abnormality to disease progression and treatment resistance." (PMID 35563039, 2022). "In this study, we conducted Sanger sequencing of formalin-fixed paraffin-embedded (FFPE) diagnostic tumor samples using a target-panel to search for recurrent mutations involving the IDH-1/IDH-2, TET-2, DNMT3A and RhoA genes in 59 cases of nMTCL." (PMID 36536430, 2022). "Epigenetic alterations relating to histone methylation (KMT2D, KMT2C, EZH2), histone acetylation (CREBBP, EP300), and DNA methylation (TET2) play an important role in tumor progression for FL and DLBCL." (PMID 36497332, 2022).
tumor (continued). "Collectively, our data revealed a Bcl6-driven and Tet2-mediated regulatory circuitry that dynamically controlled SMM-specifying program during tumor development." (PMID 36542153, 2022). "Further analysis revealed that 19 out of 20 DNA methylation regulators were upregulated in tumor samples except TET2, although the expression of TET2 in tumor tissues is higher than in normal liver tissues." (PMID 36091162, 2022). "In contrast, the expressions of NSUN3, NSUN4, NSUN7, TRDMT1, DNMT1, YBX1, and TET2 were low in tumors and had a tumor-suppressive effect." (PMID 36661693, 2022). "The genes most commonly mutated in clonal hematopoiesis are the epigenetic regulators DNMT3A and TET2, and other commonly mutated genes include regulators of HSC proliferation and tumor suppression." (PMID 36097025, 2022). "Supportively, our data demonstrated that Tet2 was remarkably induced upon Bcl6 expression and reduced by Bcl6 deletion in tumor-conditioned macrophages." (PMID 36542153, 2022). "A focus for future research will be to identify which genes have altered 5mC and/or 5hmC in tumours overexpressing TET2." (PMID 34905094, 2022). "The tumor cells of AITL, DLBCL, and MDS in this patient shared common mutations in TET2 and DNMT3A, suggesting that hematologic malignancies in the three lineages evolved from a common founder clone." (PMID 35846192, 2022). "In HCC, TET1 and TET2 have been reported to be downregulated in tumor tissues and regulate DNA methylation." (PMID 35795047, 2022). "Specifically, Vit-C stimulates TET2, which in turn activates IRF1, which eventually binds to STAT1, to enhance the expression of PD-L, making tumor cells more susceptible to immunotherapy." (PMID 35745630, 2022). "Patient-derived IDH1/2 wild-type GSC self-renewal and capacity to grow as tumor xenografts are shown to be enhanced by shRNA hairpins that repress TET2 and 5hmc levels." (PMID 35136034, 2022). "We showed that the SOX2 reprogramming TF that drives GBM cell stemness and tumor-propagating potential induces miR-10b-5p that targets TET2 that we show inhibits GBM cell stemness and GBM xenograft growth." (PMID 35136034, 2022). "According to FIGO, TET1 and TET2 expression were lower than in neoplasms classified as stage I and II in more advanced tumors." (PMID 35409163, 2022). "Our qRT-PCR analysis revealed elevated expression levels of NOP2 and NSUN6, but decreased expression of TET2 were in the tumor tissues compared to those in the paired normal tissues of 15 ccRCC samples obtained from FPH (p < 0.05)." (PMID 35309925, 2022). "A study found that TET2 was significantly correlated with tumor-related fibroblast infiltration in OCs." (PMID 36545327, 2022). "In later stages of B-cell differentiation, Tet2 functions as a tumor suppressor for mature B-cell malignancies by regulating germinal center (GC) B-cell exit of the GC reaction and plasma cell differentiation." (PMID 36203205, 2022). "Overexpression of TET2 increased 5-hmC levels and inhibited cell proliferation, invasion and migration in cell culture, and inhibited tumour growth in a xenograft model." (PMID 36050369, 2022). "TET2 DNA dioxygenase plays an important role in regulating cell identity and inhibiting tumor development by regulating DNA methylation and the expression of a large number of genes." (PMID 35480097, 2022). "In conclusion, in contrast to other IDH-related neoplasms, TET2 overexpression is common in iCCA of both subtypes, and its high expression, potentially induced by promoter hypomethylation, is an independent poor prognostic factor." (PMID 34905094, 2022). "Deletion of TET2 in tumor cells represses the expression of the checkpoint protein PD-L1 and the production of Th1-type chemokines CXCL9, CXCL10, and CXCL11." (PMID 36203205, 2022). "Our results suggest that TET2 suppresses GBM cell stemness and malignancy and predict that loss of TET2 with consequent diminished 5hmC will enhance GBM cell stemness and tumor aggressiveness." (PMID 35136034, 2022).